LAS1L (LAS1 like ribosome biogenesis factor)
Description:
Required for the synthesis of the 60S ribosomal subunit and maturation of the 28S rRNA. Functions as a component of the Five Friends of Methylated CHTOP (5FMC) complex; the 5FMC complex is recruited to ZNF148 by methylated CHTOP, leading to desumoylation of ZNF148 and subsequent transactivation of ZNF148 target genes. Required for the efficient pre-rRNA processing at both ends of internal transcribed spacer 2 (ITS2).
Synonyms: FLJ12525; Las1; Las1-like; MRXSWTS; WTS; dJ475B7.2
Tractability: Small molecule: a structure with a bound ligand is known. PROTAC: UniProt records ubiquitination sites on it; ubiquitination databases record sites on it; its protein half-life has been measured.
Target class: Enzyme; Hydrolase
Gene: Protein-coding gene on chromosome X (65,438,549 to 65,534,818, reverse strand). Ensembl gene ENSG00000001497.
Subcellular location: Nucleus, nucleolus; Nucleus, nucleoplasm; Cytoplasm
Subcellular location (Human Protein Atlas): Nucleoplasm; Basal body; Centriolar satellite; Centrosome; Cytosol; Primary cilium transition zone
Pathways (Reactome):
Metabolism of RNA: Major pathway of rRNA processing in the nucleolus and cytosol
Gene Ontology:
Molecular function: protein binding; RNA binding; endonuclease activity
Biological process: rRNA processing; cleavage in ITS2 between 5.8S rRNA and LSU-rRNA of tricistronic rRNA transcript (SSU-rRNA, 5.8S rRNA, LSU-rRNA); maturation of 5.8S rRNA; maturation of LSU-rRNA
Cellular component: membrane; MLL1 complex; nucleolus; nucleus; rixosome complex; cytoplasm; nucleoplasm; Las1 complex
Gene-disease validity (ClinGen):
ClinGen rates the evidence that LAS1L causes each of these diseases.
X-linked syndromic intellectual disability (X-linked): Limited.
Homologues: Orthologues: chimpanzee LAS1L (99% identical), macaque LAS1L (99% identical), dog LAS1L (86% identical), pig LAS1L (86% identical), guinea pig LAS1L (78% identical), rabbit LAS1L (73% identical), mouse Las1l (71% identical), rat Las1l (68% identical), tropical clawed frog las1l (33% identical), zebrafish las1l (30% identical), Drosophila melanogaster CG32075 (15% identical), Caenorhabditis elegans Y6B3B.9 (13% identical).
Diseases named in the same sentence as LAS1L in open-access papers:
LAS1L is named in the same sentence as 15 diseases in open-access papers, as found by Europe PMC text mining. Sharing a sentence is not in itself a finding about the gene and the disease. The quoted sentences say what the papers report.
triple-negative breast carcinoma (3 papers, 2022 to 2024). An invasive breast carcinoma which is negative for expression of estrogen receptor (ER), progesterone receptor (PR), and human epidermal growth factor receptor 2 (HER2). "A recent study from Dr. Samant also showed that knockdown of LAS1L leads to a reduction in proliferation and metastatic potential of triple negative breast cancer cells." (PMID 35814393, 2022). "Among them, Dr. Samant ‘s research shows that knockdown of LAS1L leads to a sharp reduction in tumorigenic and metastatic properties in triple-negative breast cancer, which is similar to Dr. Vincent’s conclusion." (PMID 35814393, 2022).
breast carcinoma (1 paper, 2021). "Breast cancer patients with higher LAS1L expression levels show significantly poor prognosis (P = 0.029)." (PMID 33664239, 2021). "Since LAS1L is a transcriptional target of β-catenin, we evaluated if breast cancer specimens with high LAS1L expression show an elevated number of nucleoli." (PMID 33664239, 2021). "Here we demonstrate that LAS1L protein expression is significantly elevated in TNBC patients, and it functionally is important for mammary tumor growth in xenograft models and enables invasive attributes." (PMID 33664239, 2021).
lung carcinoma (1 paper, 2022). "To identify tumor-specific differential splicing genes, we compared the splicing events of these genes in the TCGA SpliceSeq database and only to found that the exon 9 skipping of LAS1L was specific in lung cancer compared to normal tissue." (PMID 35814393, 2022). "In summary, our findings reveal the tumorigenic effects of hnRNPA1 and its downstream LAS1L- isoform in lung cancer cell metastasis and EMT transition." (PMID 35814393, 2022). "Our results indicate that hnRNPA1 can affect the metastasis of lung cancer cells by modulating the AS of LAS1L exon 9, highlighting the potential significance of hnRNPA1 in lung cancer metastasis." (PMID 35814393, 2022). "More importantly, our data showed that hnRNPA1 depletion can inhibit exclusion of LAS1L exon 8 to produce the LAS1L-L protein isoform, thus promoting EMT transition and metastasis capacity of lung cancer cells in vivo." (PMID 35814393, 2022).
pancreatic adenocarcinoma (1 paper, 2021). "For example, LAS1L and SENP3, as components of the MLL1-WDR5 super complex, regulate pancreatic adenocarcinoma gene transcription by affecting chromatin remodelling." (PMID 33976726, 2021).
pancreatic cancer (1 paper, 2019). "The LAS1L gene is essential for cell proliferation and also for biogenesis of the 60S ribosomal subunit and has been previously related with pancreatic cancer." (PMID 30940089, 2019).
respiratory failure (1 paper, 2022). The significant impairment of gas exchange within the lungs resulting in hypoxia, hypercarbia, or both, to the extent that organ tissue perfusion is severely compromised. "Mutations in the LAS1L gene can be associated with Wilson−Turner syndrome (WTS) and, much more rarely, severe infantile hypotonia with respiratory failure." (PMID 35627110, 2022).
tumor (3 papers, 2021 to 2024). "We also find that hnRNPA1 can directly regulate the exon skipping of LAS1L exon 9, which further promote the tumor metastasis and EMT transition." (PMID 35814393, 2022). "In this study, we found that the regulation of LAS1L on tumor metastasis and EMT transition is dominated by LAS1L-L rather than LAS1L-S." (PMID 35814393, 2022). "LAS1L-silenced cells showed comparable tumor take rates; however, tumor growth was significantly reduced." (PMID 33664239, 2021). "Most noticeable was the reduced in vivo tumor growth rates following LAS1L silencing and the impaired ability to metastasize that was reflected in reduced incidence of metastasis to lungs." (PMID 33664239, 2021). "The crucial role of LAS1L in tumor progression is being revealed." (PMID 35814393, 2022). "Similarly, except for contributing to the ribosomal biogenesis, LAS1L has also been reported to be involved in tumor cell proliferation, metastasis and autophagy." (PMID 35814393, 2022). "We then analyzed TNBC and non-TNBC tumor tissues for LAS1L protein levels using immunohistochemistry." (PMID 33664239, 2021). "However, studies on the AS regulation of LAS1L in tumor have not been reported." (PMID 35814393, 2022).
cancer (1 paper, 2021). A tumor composed of atypical neoplastic, often pleomorphic cells that invade other tissues. "Prognostic genes include LAS1L, SUPT4H1, FAM72A, C11orf31 and MRPS22, which play key roles in the biological mechanisms of cancer." (PMID 33976726, 2021).
neuromuscular disease (1 paper, 2021). "LAS1L has functions related to nervous system development, and mutations in this gene have been reported to cause mental retardation and neuromuscular disease." (PMID 33892623, 2021).
LAS1L also shares sentences with these, for which no sentence is quoted: autism (2 papers); Cerebellar atrophy (1); colorectal cancer (1); multiple myeloma (1); neurodevelopmental disorder (1); Truncal obesity (1).